EPAS1 (endothelial PAS domain protein 1)
Diseases named in the same sentence as EPAS1 in open-access papers (continued):
Sharing a sentence is not in itself a finding about the gene and the disease.
colon carcinoma (57 papers, 2009 to 2025). "The novel findings of EPAS1 mutation in cancer tissues from colon cancer might be involved in carcinogenesis." (PMID 34250767, 2021). "Similarly, herein, the suppression of EPAS1 via silencer siRNA‐sequence caused the inhibition of proliferation, colony formation of colon cancer cells significantly when compared to that of control groups." (PMID 34250767, 2021). "Also, suppression of EPAS1 in colon cancer cells caused inhibition of membrane penetrations and invasion, implying poorer metastatic ability of these cells." (PMID 34250767, 2021). "The split violin plot diagram revealed that the expression profiles of these core genes in different databases of colon cancer were higher in tumors than in healthy tissues, except for EPAS1, and the results were statistically significant." (PMID 36324584, 2022). "In this study, we have noted a similar trend where silencing of EPAS1 in colon cancer cells remarkably suppressed migration and wound healing potential of colon cancer cells." (PMID 34250767, 2021). "The hypermethylation and mRNA downregulation noted in the CMT tissue is however concurrent with previous studies where EPAS1 has been shown to be hypermethylated in its promotor with downregulated mRNA expression in non-small cell lung cancer and colon cancer." (PMID 33218035, 2020). "According to the colon cancer Cox regression test and Kaplan–Meier (K-M) curves of key genetic risk factors, the five most significant genes selected were: ELAV-like RNA-binding protein 1 (ELAVL1), GPX2, EPAS1, SLC7A5, and high mobility group box 1 (HMGB1)." (PMID 36324584, 2022). "EPAS1 was silenced in colon cancer cells by siRNA followed by cell proliferation, invasion and migration of EPAS1 suppressed (SW480−EPAS1, Lovo−EPAS1) and controlled (SW480+Scr and Lovo+Scr, SW480wildtype and Lovowildtype) cells were examined at a different time interval (days 0–3)." (PMID 34250767, 2021). "SW480−EPAS1 and Lovo−EPAS1 (EPAS1 silenced) colon cancer cells exhibited significant inhibition of wound healing, barrier penetration and migration when compared to that of controls (SW480+Scr & Lovo+Scr) and non‐transfected wild‐type (SW480wildtype & Lovowildtype) cells." (PMID 34250767, 2021). "In addition, the expression of EPAS1 mRNA in colon cancer cells was significantly higher when compared with non‐neoplastic colon epithelial cells." (PMID 34250767, 2021). "Also, reduced cell proliferation, wound healing, migration and invasion were noted in colon cancer cells followed by EPAS1 silencing." (PMID 34250767, 2021). "In addition, EPAS1 DNA copy number and mRNA expression changes and their clinicopathological correlations as well as EPAS1 induced cellular changes in colon cancer cells were investigated." (PMID 34250767, 2021). "Although a separate study showed EPAS1 to be hypomethylated in colon cancer." (PMID 33218035, 2020). "Our results suggest that five core genes, ELAVL1, GPX2, EPAS1, SLC7A5, and HMGB1, are involved in the ferroptosis of colon cancer cells." (PMID 36324584, 2022). "We identified five core genes, ELAVL1, GPX2, EPAS1, SLC7A5, and HMGB1, involved in the ferroptosis of colon cancer." (PMID 36324584, 2022). "As shown in the interaction network, immune-related gene PLCG2 and IGF1, which are up-regulated in colon tumor samples, have significantly strong correlation with several TFs: FOXP3, IKZF1, CBX7, LMO2, MEF2C, EPAS1 and MAF." (PMID 33996273, 2021). "Suppression of EPAS1 in colon cancer cells (SW480−EPAS1 and Lovo−EPAS1) induced the reduction of colony formation rates significantly when compared to SW480+Scr and Lovo+Scr and non‐transfected SW480wildtype & Lovowildtype control colon cancer cells." (PMID 34250767, 2021).
colon carcinoma (continued). "In addition to the expected association with anaemia-related phenotypes, the only other Bonferroni-significant associations of individual biological pathways that persisted in colocalization were EPAS1 with hypertension and SLC25A28 with colorectal cancer and benign neoplasm of colon." (PMID 39643614, 2024).
lung cancer (57 papers, 2008 to 2025). A malignant neoplasm involving the lung. "Xu’s team found that EPAS1 gene is dysregulated in non–small cell lung cancer, which encodes hypoxia-inducible factor 2α and plays an important role in the progression of non–small cell lung cancer." (PMID 33747044, 2021). "The death risk for lung cancer patients with suppressed EPAS1 expression levels was found to be 1.478 times higher than that of patients with elevated EPAS1 expression levels (95% CI: 1.087-2.008)." (PMID 34729113, 2021). "Studies have shown that EPAS1 is associated with treatment resistance, metastasis and poor clinical prognosis among patients with lung cancer." (PMID 32686362, 2020). "Our data cannot address the specific role of EGLN1 and EPAS1 genetic variants in lung cancer initiation, progression, or survival." (PMID 28036300, 2017). "Here, we ascertained the frequencies of EGLN1D4E/C127S and EGLN1C127S variants and ten EPAS1/HIF-2α variants in lung cancer patients and controls in Nepal, whose population consists of people with Indo-Aryan origin and Tibetan-related Mongoloid origin." (PMID 28036300, 2017). "However, we conclude that high-altitude adapted Tibetan variants in the EGLN1 and possibly EPAS1 regions are associated with the modified lung cancer risk, and that the role of these Tibetan evolutionary selected haplotypes needs to be further elucidated." (PMID 28036300, 2017). "Hypoxia-inducible factor-2α (also called endothelial periodic acid-Schiff domain protein 1, EPAS1) seems to play an important role in some carcinogenesis, though there is no information on the relationship between single nucleotide polymorphism(SNP) of EPAS1 and lung cancer development so far." (PMID 26985396, 2016). "In conclusion, we found here for the first time that nucleotide difference at the rs13419896 SNP may affect EPAS1 gene and protein expression, specifically in response to AP-1, and that the A allele of EPAS1 SNP is associated with poorer prognosis of lung cancer patients." (PMID 26263511, 2015). "In lung cancer cells, EPAS1 overexpression abrogated the inhibitory effects of miR-383 on cell expansion." (PMID 36313570, 2022). "In human lung cancer cells, miR-383, via inhibiting the expression of EPAS1, repressed the wound healing capacity and invasive capacity of lung cancer cells." (PMID 34976192, 2022). "In lung cancer patients, EPAS1 overexpression in malignant tissues was related to an unfavorable prognosis." (PMID 36313570, 2022). "In the miR‐383/EPAS1 pathway, miR‐383 prevents lung cancer development by targeting the 3′-UTR of EPAS1 mRNA." (PMID 36313570, 2022). "Here, we demonstrated that LINC01436 regulated the expression of EPAS1 and its target genes in lung cancer cell lines, including angiogenesis (VEGFA) and metabolism reprogramming (GLUT1) genes." (PMID 30614188, 2019). "EPAS1, also named HIF‐2α, was associated with therapy resistance, metastasis and poor clinical prognosis in various cancers, including lung cancer." (PMID 30614188, 2019). "In lung cancer, TRM cells had elevated expression of genes related to hypoxia, such as HIF1A (which encodes HIF-1α) and EPAS1 (which encodes HIF-2α)." (PMID 30180905, 2018). "We evaluated the association between lung cancer and Tibetan-specific EGLN1 and EPAS1 genetic variants." (PMID 28036300, 2017). "Other researchers have evidenced that in murine models of lung cancer, high expression levels of EPAS1 relate to tumor of large size, invasion and angiogenesis." (PMID 28830341, 2017). "In our case-control study, we evaluated association between lung cancer and Tibetan-specific evolutionary selected EGLN1 variants, EGLN1D4E and EGLN1C127S and ten EPAS1 SNPs with strong evidence of positive selection." (PMID 28036300, 2017). "We further analyzed levels of EPAS1 (HIF-2α) protein expression in several lung cancer cell lines by immunoblotting analyses." (PMID 26263511, 2015).
lung cancer (continued). "Similarly, lung cancers are mostly suppressed by miR-184 via EPAS1, CDC25A, and c-MYC targeting, although chemotherapy resistance studies reveal occasional tumour-promoting roles." (PMID 41379397, 2025). "Our study showed LINC01436 acts as a ceRNA to regulate EPAS1 by sponging miR‐30a‐3p in lung cancer." (PMID 30614188, 2019). "Therefore, miR-182-5p promotes lung cancer invasion and metastasis by negatively regulating EPAS1." (PMID 34729113, 2021). "In addition, we observed a two-fold increase in the risk of lung cancer for two of ten interrogated EPAS1 SNPs, although the associations were not significant after correction for multiple testing." (PMID 28036300, 2017). "EPAS1 is upregulated in PAH and downregulated in eight datasets of lung cancer, suggesting that it could be an important oncogene during the lung cancer tumorigenic process." (PMID 36661515, 2023).
anemia (52 papers, 2009 to 2026). A reduction in the number of red blood cells, the amount of hemoglobin, and/or the volume of packed red blood cells. "In a study by Gruber M, both newborn and adult rats with EPAS1 knockout presented with anemia or severe pancytopenia with suppressed EPO production, indicating the pro-erythrocytosis effect of HIF-2α by transcriptionally regulating EPO production." (PMID 36923253, 2023). "Toshiharu Y illustrated, however, that HIF-2α governs erythropoiesis by specifically regulating vascular adhesion molecule-1(VCAM-1) expression in ECs to maintain the hematopoietic microenvironment compared to normocytic anemia in mice with EPAS1 knockdown." (PMID 36923253, 2023). "A lack of HIF in mice results in anemia, and EPAS1 haplotypes, which affect the production of HIF-2α, are associated with low Hb in Tibetans." (PMID 35188068, 2022).
pheochromocytoma (51 papers, 2009 to 2026). "Mutations in the EPAS1 sequence are associated with several neoplasms, including paraganglioma, pheochromocytoma and pancreatic adenocarcinoma." (PMID 34250767, 2021). "Germline and somatic variants around important PTMs for EPAS1 stability were extensively associated with the development of the erythrocytosis type 4 and neuroendocrine tumors paraganglioma and pheochromocytoma." (PMID 34828399, 2021). "Patients referred to the NIH for new, recurrent, and/or metastatic paraganglioma or pheochromocytoma were confirmed for EPAS1 gain-of-function mutation; imaging was evaluated for vascular malformations." (PMID 33497361, 2021). "Mutations of EPAS1 has been identified in various cancers such as in paraganglioma, pheochromocytoma, and pancreatic carcinomas." (PMID 33042797, 2020). "In phaeochromocytomas, 12% (n = 7/57) of patients had mutations in the EPAS1 sequence, which includes two novel mutations (c.1091A>T; p.Lys364Met and c.1129A>T; p.Ser377Cys)." (PMID 33114456, 2020). "Herein, we investigated mutations in EPAS1 in a cohort of phaeochromocytoma (n = 57) or paraganglioma (n = 14) and have described the clinical, molecular and genetic features of patients carrying somatic EPAS1 mutations." (PMID 33114456, 2020). "Among the seven patients with phaeochromocytoma harbouring mutated EPAS1, two patients had clinical confirmation of neurofibromatosis 1 (case 94 and case 122)." (PMID 33114456, 2020). "The current study reports EPAS1 mutations in patients with phaeochromocytomas and paragangliomas and their correlation with various clinicopathological factors." (PMID 33114456, 2020). "This study identified novel mutations and clinicopathological implications of EPAS1 dysregulation in the pathogenesis of phaeochromocytoma/paraganglioma." (PMID 33114456, 2020). "This study aims to identify EPAS1 mutations and alterations in DNA copy number, mRNA and protein expression in patients with phaeochromocytomas/paragangliomas." (PMID 33114456, 2020). "This study has reported multiple novel EPAS1 mutations in patients with phaeochromocytomas/paragangliomas." (PMID 33114456, 2020). "The association of molecular dysregulations of EPAS1 with clinicopathological factors in phaeochromocytomas and paragangliomas were also analysed." (PMID 33114456, 2020). "Previous studies reported that dysregulation and gain-of-function mutation of EPAS1 associated with neuroendocrine tumours such as paraganglioma and phaeochromocytomas by inducing pseudo-hypoxic tumour microenvironment." (PMID 33114456, 2020). "Recent studies have demonstrated that mutations in endothelial PAS domain-containing protein 1 (EPAS1) is associated with manifestations of phaeochromocytomas and paragangliomas." (PMID 33114456, 2020). "Mutations of the EPAS1 gene, which codes for the HIF-2α, have been described in 6% of patients with pheochromocytoma and paraganglioma and strongly suggest a pathogenic and, therapeutically speaking, targetable role for hypoxia." (PMID 29892268, 2018). "In this case EPAS1 mutation was detected in pheochromocytoma." (PMID 40290304, 2025). "Molecular pathology showed EPAS1 mutation in pheochromocytoma." (PMID 40290304, 2025). "In addition, EPAS1 has associated with various diseases, such as non-small cell lung cancer, paraganglioma and pheochromocytoma, and chronic mountain sickness, which can regulate proliferation of erythroblasts." (PMID 37495990, 2023). "The identification of somatic mutations affecting EPAS1 in phaeochromocytomas and paragangliomas led to the hypothesis that the stabilization of HIF-α plays crucial roles in the development of chromaffin tumours through the phenomenon known as pseudo-hypoxia." (PMID 33114456, 2020). "Moreover, the DNA amplification and mRNA overexpression in patients with phaeochromocytomas/paragangliomas bearing EPAS1 mutations is indicative of the concerted aberration of EPAS1 in the pathogenesis for this group of tumours." (PMID 33114456, 2020).
pheochromocytoma (continued). "Similarly, the dysregulated expression of EPAS1 mRNA in tumour samples indicated the tumour-associated functionality of EPAS1 in phaeochromocytomas and paragangliomas." (PMID 33114456, 2020). "So far, EPAS1 mutations have been reported in a few phaeochromocytomas and paragangliomas." (PMID 33114456, 2020). "Furthermore, gain-of-function mutations (p.Phe374Tyr and p.Met368Ile) in exon 9 EPAS1 in phaeochromocytomas/paragangliomas associated with the increased stability of HIF2α." (PMID 33114456, 2020). "Therefore, further research on the effects of EPAS1 mutation on gene expression in a large cohort of patients with phaeochromocytomas and paragangliomas is critical to unveil its roles in the phaeochromocytomas/paragangliomas pathogenesis." (PMID 33114456, 2020). "EPAS1 mutations have been identified in several pathological conditions in humans, including congenital heart disease, erythrocytosis, Lynch syndrome, polycythaemia and in various tumours, e.g., in paraganglioma, phaeochromocytoma, pancreatic adenocarcinoma." (PMID 33114456, 2020). "In addition to the somatic mutation of EPAS1, inherited and constitutional mutations were associated with the pathogenesis of phaeochromocytoma and paragangliomas." (PMID 33114456, 2020). "In addition, various tumors, e.g., paraganglioma, pheochromocytoma, and pancreatic adenocarcinoma, showed mutations in EPAS1 sequences." (PMID 33042797, 2020). "In addition, higher expressions of EPAS1 protein in mutated samples indicate tumour-supporting roles of EPAS1 in the pathogenesis of phaeochromocytoma/paraganglioma." (PMID 33114456, 2020). "Somatic mutations of BRAF and RAD54B were detected in Langerhans cells and EPAS1 in pheochromocytoma." (PMID 40290304, 2025). "Among the tumours (phaeochromocytomas, n = 37; paragangliomas, n = 8), 53% (n = 24/45) showed high levels of EPAS1 mRNA expression, whereas 47% (n = 21/45) had EPAS1 low-level expression." (PMID 33114456, 2020). "Many patients with tumours located in the adrenal gland (phaeochromocytomas) showed EPAS1 DNA amplification when compared to those with tumours outside adrenal gland (paragangliomas) (84.21% versus 57.14%; p = 0.037)." (PMID 33114456, 2020). "In the present study, genetic alterations in the EPAS1 sequence were noted in 12% (7/57) of phaeochromocytoma tumours." (PMID 33114456, 2020). "In the current study, the aberrant EPAS1 DNA number in patients with phaeochromocytomas/paragangliomas implied its potential roles in carcinogenesis." (PMID 33114456, 2020). "One previous report on the effects of reactivated EPAS1 expression in mouse pheochromocytoma cells in vitro provides evidence that HIF-2α downstream signaling may be involved in SSTR2 downregulation." (PMID 36946182, 2023). "Consistent with our previous findings that HIF2α promoted a pro-metastatic phenotype in pheochromocytoma cells, activation of hypoxia signaling pathways through enhanced expression of Epas1 also led to enhanced pro-metastatic properties in our novel sub-cell lines." (PMID 35159368, 2022). "The single carotid body PGL in this series, which arose in the same patient with an EPAS1 mutant pheochromocytoma, also did not carry a somatic EPAS1 mutation." (PMID 34572828, 2021). "The statistical relationship of EPAS1 DNA amplification and increased mRNA expression in patients with phaeochromocytomas/paragangliomas in this study indicated that hypoxic tumour niche induces molecular alterations of EPAS1, which, in turn, can promote carcinogenesis." (PMID 33114456, 2020). "Among the EPAS1 mutation-positive tumour samples (phaeochromocytomas, n = 7; paragangliomas, n = 1), 37.5% showed no change or low expression and 62.5% of samples had high EPAS1 protein expression." (PMID 33114456, 2020). "Moreover, all paragangliomas showed low EPAS1 mRNA expression, whereas 35% of phaeochromocytomas had low EPAS1 mRNA expression (p = 0.001)." (PMID 33114456, 2020).